IL1B (interleukin 1 beta)
Diseases named in the same sentence as IL1B in open-access papers (continued):
Sharing a sentence is not in itself a finding about the gene and the disease.
memory impairment (continued). "Additionally, EA stimulation in Aβ25-35-treated rats can downregulate IL-1β and TNF-α in the prefrontal cortex and hippocampus, attenuating inflammatory responses and improving memory impairment." (PMID 38274501, 2023). "Interestingly, once recombinant IL-1β was delivered to the left hippocampus, the GW4869-exerted obvious ameliorative effects on memory impairment including behavioral score, distance, and latency time of platform were all abolished." (PMID 35111693, 2021). "Strawberry and selenium, when administered individually, significantly attenuated memory impairment, oxidative stress, neuroinflammation, and apoptosis, as evidenced by marked normalization of Nrf2/HO-1, TAC, SOD, MDA, TLR4/NF-κB/TNF-α, NLRP3/CASP-1/IL-1β, and BAX/Bcl-2 signaling." (PMID 41471381, 2025). "Previous studies also demonstrated that moxibustion could inhibit chemotaxis and cell migration into inflamed tissues by promoting neutrophil apoptosis and downregulating cytokines, such as IL-1β, IL-17, IFN-γ, and TNF-α, to improve inflammatory status and memory impairments." (PMID 38274501, 2023). "Nevertheless, both IL-1β and BDNF are recognized as key players (upstream of Synapsin-1) in synaptic plasticity, and their dysregulation may also correspond to hippocampal related memory impairments." (PMID 26566284, 2015). "Similarly, our findings indicated that MISO significantly increased the levels of pro‐inflammatory factors (IL‐6, IL‐1β, and TNF‐α) and decreased that of the anti‐inflammatory factor IL‐10 in the hippocampus of offspring mice, which contributed to the observed spatial learning and memory impairment." (PMID 38945806, 2024). "Although how LPS mediates memory impairment is still poorly understood, the changes in the expression of some inflammatory-related genes, especially Il1b, but not obviously in the expression of MHC II-related genes, may be theoretically linked with memory impairment." (PMID 37892969, 2023).
osteoporosis (91 papers, 2010 to 2026). A condition of reduced bone mass, with decreased cortical thickness and a decrease in the number and size of the trabeculae of cancellous bone (but normal chemical composition), resulting in increased fracture incidence. "Previous studies have confirmed that M1 macrophages, in the context of osteoporosis and inflammatory bone loss, can facilitate osteoclastogenesis and bone resorption by secreting pro-inflammatory cytokines such as IL-1β and TNF-α." (PMID 41246341, 2025). "Phenotypically, one study found that individuals carrying the rs1143630 G allele were predisposed to osteoporosis in the Chinese population, potentially due to the more potent effect of IL‐1β on osteoclast precursor differentiation into mature osteoclasts." (PMID 37937732, 2024). "IL-1β variants rs1143627, rs16944, and rs1143623 are related to elevated susceptibility to osteoporosis, especially in women older than 60 or with a BMI greater than 24 kg/m2." (PMID 36831188, 2023). "The study in postmenopausal women with osteoporosis demonstrated that single-nucleotide variants in NLRP3 inflammasome pathway genes activating pro-inflammatory cytokines IL-1β and IL-18 production are associated with osteoporosis severity." (PMID 37958752, 2023). "It has been observed that some risk factors of osteoporosis increase the production of proinflammatory cytokines, particularly IL-1β and IL-6, and can decrease OPG serum levels." (PMID 34497849, 2021). "In fact, IL-1β is a multifunctional and highly potent pro-inflammatory cytokine that was confirmed to be associated with bone resorption and osteoporosis in some inflammatory diseases." (PMID 33602312, 2021). "Subsequently, we also examined effects of intravenous infusion of IL1β priming TMSCs on recovery from bone loss in ovariectomized osteoporosis mouse model." (PMID 34115339, 2021). "High expression levels of NLRP3 inflammasome and IL-1β deteriorate osteoporosis under estrogen deficiency by inhibiting osteogenic differentiation." (PMID 31146750, 2019). "In the last years, some specific polymorphisms of the IL-1β and IL-1Ra genes have been associated with an increased risk of osteoporosis." (PMID 25954061, 2015). "More recently, the IL-1β (-511C/T) polymorphism has been associated with an earlier insurgence of osteoporosis in postmenopausal women." (PMID 25954061, 2015). "Several cytokines such as TNF-α, IL-1β, and IL-6 were implicated in the pathogenesis of osteoporosis." (PMID 23936022, 2013). "These experimental results suggest that the pathogenesis of osteoporosis is associated with IL-1β (-511C/T) polymorphism in postmenopausal women." (PMID 20940514, 2010). "Elevated IL-1β levels are linked to bone loss in osteoporosis." (PMID 38656061, 2024). "For instance, it was demonstrated that patients with herpes zoster infections presented with a 4.55-fold greater risk of osteoporosis, as associated with significantly high levels of interleukin (IL)-1b, IL-6, IL-8, IL-10, and tumor necrosis factor-alpha (TNF-α)." (PMID 37113002, 2023). "Additionally, He and collaborators (2020) demonstrated an association between IL-1β genetic variants and osteoporosis predisposition." (PMID 36831188, 2023). "Osteoporosis caused by ovariectomy was not only mediated by overactivated osteoclast activity but inflammation, serological results indicated that dimemorfan also reduced IL‐1β, IL‐6, and TNF‐α secretion." (PMID 35611810, 2022). "Additionally, He and colleagues investigated IL-1β genetic variants and predisposition to osteoporosis among the northwestern Chinese Han population." (PMID 36553538, 2022). "Collectively, our data revealed that targeting IL-1β may be a promising strategy to inhibit inflammation-associated bone destruction and osteoporosis." (PMID 23403591, 2013). "There was a significant association between the IL-1β (-511C/T) gene and osteoporosis." (PMID 20940514, 2010).
osteoporosis (continued). "A significant gene-gene interaction between ESR1 (rs2228480) and RANK (rs3018362) increased osteoporosis risk (OR = 2.1 [1.4-3.2], CVC = 10/10), and a gene-gene model involving ESR1, IL6R, IL1β, and RANKL was identified for hip fracture (CVC = 8/10)." (PMID 41929826, 2026). "Inflammatory mediators such as tumor necrosis factor-alpha (TNF-α), interleukin-1 beta (IL-1β), and interleukin-6 (IL-6), which are elevated in both osteoporosis and neurodegenerative diseases, serve as common mechanistic links." (PMID 41007423, 2025). "Therapeutic strategies targeting these inflammatory cytokines, such as the use of biologics that inhibit TNF-α or IL-1β, are being explored as potential interventions to modulate bone turnover in osteoporosis." (PMID 38656061, 2024). "Inflammatory factors such as IL-1β and IL-18 contribute to osteoporosis pathogenesis through caspase-activated cellular pyroptosis." (PMID 38994021, 2024). "Further joint degeneration is brought on by IL‐1β's promotion of osteoporosis and cartilage destruction in joints." (PMID 39479687, 2024). "Estrogen deficiency curtailed osteogenic differentiation of BMSCs by promoting the Capsase-1/GSDMD/IL-18 and IL-1β pyroptosis pathways, culminating in osteoporosis, while NLRP3 knockdown fostered bone formation." (PMID 38895114, 2024). "Pro-inflammatory cytokines, such as IL6 and IL1β, contribute significantly to the phenomenon of inflammation, both during sarcopenia and osteoporosis, also enhancing PGE2." (PMID 38892069, 2024). "NFKB1, IL-1β, and RelA had an increased binding potency which mainly explains Quercetin’s anti-osteoporosis activity." (PMID 36839278, 2023). "Subsequent cellular studies confirmed that lncMIAT promoted the secretion of IL-6, TNF-α and IL-1β, which were important inflammatory cytokines for the disease progression of osteoporosis." (PMID 35381577, 2022). "The significant inhibition of IL-1β and NO production by chlorogenic acid indicates that it plays an important role in preventing and treating osteoporosis." (PMID 35487926, 2022). "In bone tissue, IL-6 stimulates RANKL, which is indispensable for osteoclast differentiation and activation, and its effect would be in conjunction with that of IL-1β, leading to bone resorption and osteoporosis." (PMID 36184700, 2022). "Overall, these results suggested that IL1β priming TMSCs have potential to restore bone homeostasis in osteoporosis." (PMID 34115339, 2021). "In this study, IL1β priming TMSCs were systemically infused in ovariectomized postmenopausal osteoporosis (OVX) model mice established by combining full bilateral ovariectomy with low calcium diet to insure bone mineral loss." (PMID 34115339, 2021). "It has been reported that human peripheral-blood monocytes (PBMCs) from osteoporosis patients have 29–67% higher secretion of IL-1β, IL-6, and TNF-α in whole blood culture compared with healthy control subjects." (PMID 34917622, 2021). "Upregulation of IL-1β, enhanced osteoclastogenesis, and decreased osteogenesis are observed in osteoporosis, partly because of inflammasome activation." (PMID 34177950, 2021). "In pathological condition in osteoporosis, pro-inflammatory cytokines such as tumor necrosis factor alpha (TNFα), IL1β, and IL17 were increased." (PMID 34115339, 2021). "Another study confirmed that Om-PDRN also exhibited an anti-osteoporosis effect on chondrosarcoma cells stimulated with 10 ng/mL of IL-1β." (PMID 34067499, 2021). "For in vivo efficacy study, IL1β priming TMSCs were intravenously infused twice with ovariectomized (OVX) osteoporosis mouse model, and blood serum and bone parameters from micro computed tomography images were analyzed." (PMID 34115339, 2021). "A SNP in the IL-1β gene (rs16944 C > T, also known as IL1B -511T) has also been found to be associated with osteopenia/osteoporosis and lower mineral density in CD patients." (PMID 34299046, 2021).
osteoporosis (continued). "Age-dependent osteoporosis resulted in significant increase in serum levels of phosphate, bone specific alkaline phosphatase, hsCRP, IL-1β, IL-6, TNF-α, MDA, NO, and RANKL gene expression." (PMID 32532246, 2020). "In this context, several published results confirm the role of IL-1β, to induce bone resorption and osteoporosis." (PMID 25954061, 2015). "Furthermore, an increased risk of bone loss and osteoporosis in adult patients affected by dermatomyositis/polymyositis and in patients affected by Behcet's diseases has been demonstrated which appears to be linked to inflammatory processes and production of IL-1β." (PMID 25954061, 2015). "The expressions of TNF-α and IL-1β were found to be enhanced in both animal model and patients with osteoporosis." (PMID 24348690, 2013). "Inflammatory cytokines, including IL-1β, IL-6 and TNF-α, are also responsible for the characteristic loss of bone density in osteoporosis through their effect on osteoclast activity." (PMID 22176920, 2011). "In our study, the allelic and genotypic frequency results showed that IL-1β genotype was more frequent in postmenopausal Taiwanese women with osteoporosis." (PMID 20940514, 2010). "Chen et al14 reported similar findings, that IL-1β and IL-1ra gene polymorphisms were associated with BMD and osteoporosis in postmenopausal women." (PMID 20940514, 2010). "IL-1β, by binding to IL-1R, can stimulate the NF-κB pathway by a MyD88-dependent mechanism, triggering ubiquitin-proteasome system-mediated protein degradation and leading to decreased muscle mass, thus producing sarcopenia-osteoporosis systemically." (PMID 41495343, 2026). "Specifically, serum IL-1β concentration was significantly higher in the osteoporosis group." (PMID 41451124, 2025). "Consequently, an elevation in pro-inflammatory cytokines such as TNF-α and IL-1β can worsen osteoporosis as they participate in bone turnover and act as potent stimulants of bone resorption." (PMID 40125318, 2025). "Notably, unlike adefovir, tenofovir additionally contributes to the development of osteoporosis by affecting inflammatory cytokine pathways such as IL-17, IL-1β, and TNF." (PMID 40687725, 2025). "Further, in vivo and in vitro studies confirmed that OC-Exo-packaged miR-30a-3p was transferred to OBs and inhibited bone formation, possibly via targeting IKBKG to initiate caspase-1 activation and the secretion of IL-1β and IL-18, thus accelerating the progression of osteoporosis." (PMID 40110632, 2025). "Studies have indicated that acupuncture at the ST36 acupoint reduced serum IL-1β expression in ovariectomized rats; generally, acupuncture can mitigate bone destruction and slow the progression of osteoporosis by downregulating inflammatory factors such as tumor necrosis factor-α and interleukin-6." (PMID 39588119, 2024). "Additionally, IL‐1β promotes osteoporosis and cartilage damage in joints, leading to further joint degradation." (PMID 39554315, 2024). "Another gene ties to the secretion level of IL-1β, called IL1B-511*2, whose polymorphism could also be a predictor for the risk of osteopenia or osteoporosis in IBD patients." (PMID 37275908, 2023). "To study whether IL1β priming TMSCs have therapeutic potential in osteoporosis, we established an animal model for osteoporosis by surgical removal of ovaries in 7 weeks old female mice followed by low calcium diet to enhance bone loss (OVX model)." (PMID 34115339, 2021). "Since interleukin (IL) 1β is known to be one of inflammatory cytokines involved in osteoporosis progression, treatment of IL1β with TMSCs may enhance immunomodulatory function and therapeutic effects of TMSCs in osteoporosis." (PMID 34115339, 2021). "For this reason, we hypothesized that IL1β priming TMSCs have constant and enhanced therapeutic efficacy in osteoporosis." (PMID 34115339, 2021). "Therefore, the production of IL-1β by dendritic cells promotes Th17 differentiation which contributes to the development of osteoporosis." (PMID 32204562, 2020).
osteoporosis (continued). "On the other hand, there was no change in the expression of IL-6, IL-1β or IL-23a, which are cytokines associated with osteoporosis." (PMID 32443893, 2020). "In addition, inflammation is closely related to osteoporosis, in which IL-1β, TNF-α, and IL-6 can activate the macrophages of the NF-κB pathway, thereby causing them to differentiate into osteoclasts." (PMID 31470845, 2019). "Studies have shown a correlation between magnesium deficiency and osteoporosis, attributable to changes in parathyroid hormone (PTH), Vitamin D levels and increased pro-inflammatory cytokine secretion such as substance P, TNF-α, IL-1β, and RANKL." (PMID 32802092, 2019). "IL-1β and TNF-α were positively associated with NTx in osteoporosis women." (PMID 28121926, 2017). "As we observed increased levels of both IL-1β and TNF-α in P2X7MUT subjects relative to P2X7WT subjects, it might be suggested that P2X7MUT subjects have an increased risk to develop osteoporosis." (PMID 23210974, 2012). "Statistically significant differences were found in allele frequency for IL-1β when osteoporosis patients were compared with non-osteoporotic women (P<.05)." (PMID 20940514, 2010). "Thus, the maladaptation of the link between NLPRP3/Caspase1/IL-1β signaling-related inflammation and bone turnover may be a key determinant of osteoporosis." (PMID 36514079, 2022). "Therefore, we speculated that inhibition of NLPRP3/Caspase1/IL-1β signaling by exercise may be effective in anti-osteoporosis in aged rats by improving the bone microenvironment." (PMID 36514079, 2022). "Moreover, the elevated bone fracture risk, osteoporosis, and osteopenia were studied and confirmed to be present in chronic inflammatory disorders, due to the action of inflammation factors (such as IL-6, TNF, and IL-1β)." (PMID 35334519, 2022). "The expression of inflammatory factors, such as interleukin-1 beta (IL-1β), IL-6, IL-17, and TNF-α, is markedly increased as osteoporosis progresses." (PMID 40873591, 2025). "In the prospective clinical cohort, we observed a clear dose-response relationship, with IL-1β, IL-6, and TNF-α levels showing significant graded increases across the control, osteopenia, and osteoporosis groups." (PMID 41451124, 2025). "Osteoporosis has a destructive effect on bone tissue through different mechanisms: nuclear factor-κβ ligand and NLRP3/Caspase-1/IL-1β cascade." (PMID 38759999, 2024). "The expression of numerous inflammatory factors (IL-1β, IL-6, IL-17, and TNF-α) markedly increased during the progression of osteoporosis." (PMID 38895114, 2024). "In osteoporosis patients, there is a notable elevation in serum baseline levels of tryptase, IFN-γ, IL-1β, and IL-6." (PMID 38817601, 2024). "IL-1β affects both osteoblastogenesis and osteoclastogenesis and was described in the onset of OVX- and unloading/disuse-induced osteoporosis." (PMID 36282293, 2023). "Bone resorption is predominantly induced by IL-6, IL-1β and TNF-α in osteoporosis, especially in the post-menopausal patients." (PMID 35381577, 2022). "Inflammation mediated osteoporosis presented apparently down-regulated in OPN and OCN levels, higher serum IL-1β, TNF-α, IL-6 levels in ovariectomized rats." (PMID 36387862, 2022). "MLN64-knockdown alleviates the severity of osteoporosis, down-regulates specific genes related to osteoclastogenesis including Runx2 and inflammatory factors such as TNF-α, IL-1β, IL-6, and MMP-1." (PMID 36387862, 2022). "Osteoporosis is mediated by a variety of inflammatory mediators, including TNF-α, RANKL, interleukin 1 beta, IL-6, and interferon gamma." (PMID 35187034, 2022). "Serum IL-1β, IL-6, NTx, and PTH levels in women with osteoporosis were significantly higher than controls." (PMID 28121926, 2017). "WSP-AbM reduced TNF-α, IL-1β, ICAM-1, iNOS, and COX-2 expressions and osteoporosis by the inhibition of NF-κB activation." (PMID 24348690, 2013).